HK2 (hexokinase 2)
Diseases named in the same sentence as HK2 in open-access papers (continued):
Sharing a sentence is not in itself a finding about the gene and the disease.
tumor (continued). "As for HK2, it has been shown to be required for tumor initiation and maintenance, and HIF-1α has been shown to upregulate HK2 expression, leading to pro-survival and epithelial-to-mesenchymal transition in BC." (PMID 34298771, 2021). "Consistent with the in vitro data, inhibition of lncRNA MDFIC-7 expression suppressed the mRNA expression of GLUT1, HK2, PDK1 and LDHA in the xenograft tumor tissues." (PMID 34621682, 2021). "In contrast, the expression of hexokinase-2, both the total and the mitochondria fraction, was substantially decreased, implying hexokinase-2 was involved in TRAF6-mediated tumor glycolysis." (PMID 34409101, 2021). "In many types of cancer cells, when HK2 binds to VDAC1, the interaction between VDAC1 and Bcl-2 protein family will be blocked, resulting in a decrease in Cytc release, thus protecting tumor cells from apoptosis." (PMID 33680287, 2021). "The results showed that HK2, PGM1, PPP1R3C, GYS1, and G6PD were significantly up-regulated in ccRCC tumor tissues." (PMID 34522206, 2021). "The tumour growth advantage was also supported by the upregulation of pAKT1, pMTOR, pRPS6, pEIF4EBP1, MKI67, MYC and HK2 and the downregulation of hsa‐miR‐429." (PMID 34954904, 2021). "Accumulated evidence has confirmed a close connection between HK2 and the PI3K/Akt signaling pathway during abnormal glycometabolic processes and tumor malignant development." (PMID 34758823, 2021). "Consistently, we observed little effects of the HK1 or HK2 deletion in vitro; however, the HK1 deletion substantially delayed the tumor growth in vivo." (PMID 34895333, 2021). "Altogether, our results demonstrate the broad impact of replacing HK2 by GCK in HCC cells, and the key role played by the HK isoenzyme switch in HCC tumor metabolism." (PMID 33594203, 2021). "In the present study, we demonstrated that by mediating Akt ubiquitination and activation, regulating HIF-1α transcriptional activities, and hexokinase-2 expression, TRAF6 played an important role in the regulation of tumor glycolysis." (PMID 34409101, 2021). "METTL3 enhanced the stability of pyruvate dehydrogenase kinase 4 (PDK4) and HK2 mRNAs in a METTL3-m6A-YTHDF1-dependent manner, ultimately promoting tumor growth and chemoresistance." (PMID 33879256, 2021). "Since HK1 functions as a housekeeping gene in normal tissue and HK2 is upregulated in most aggressive tumors, this distinction makes the SENP1-HK2 axis an excellent target for tumor therapy." (PMID 33753739, 2021). "After coculture of autophagic CAFs with T24 cells, cell proliferation and invasion were both enhanced, along with increased expression of MCT1, MCT4, HK2, and SLC2A1, as well as elevated levels of lactate in the tumor microenvironment." (PMID 34122670, 2021). "Key glycolytic enzymes, such as hexokinase 2 (HK2), phosphofructokinase (PFK), and pyruvate kinase 2 (PKM2), are reported tumor markers." (PMID 34523732, 2021). "In an HCC mouse model, HK2 knockdown inhibited glycolysis and thus glucose flux to pyruvate and lactate, and simultaneously increased oxidative phosphorylation, which could be diminished by metformin, contributing to further cell death and the inhibition of tumor growth." (PMID 34359547, 2021). "Given that EMT is a factor in tumour metastasis, we further investigated the migration ability of CRC cells when HK2 was knocked down by Transwell and wound‐healing assays." (PMID 34378321, 2021). "The essential role of glycolytic enzymes like HK2 and PFKFB3 in maintaining the high glycolytic tumor phenotypes has been reported in recent years." (PMID 32841217, 2020).
tumor (continued). "Upregulation of hexokinase 2 (HK2), a key glycolytic enzyme in the first essential step of glucose metabolism, can induce glycolysis, crucial for tumor progression." (PMID 33419318, 2020). "The predominant role of HK2 in tumor cells is also confirmed by the observation that the tumor subgroups expressing both HK1 and HK2 are sensitive to inhibition of HK2 alone." (PMID 33008042, 2020). "Lnc UCA1, along with the enzyme hexokinase-2 (HK2), has been found to enhance glycolysis in radioresistant tumor cells, thus participating in the regulation of radiotherapy sensitivity." (PMID 32122355, 2020). "Our data showed that suppression of HK2-mediated glycolysis with small compounds, Tan IIA, inhibits OSCC cell growth and tumor formation." (PMID 32424132, 2020). "Our results indicate that HKDC1 expression plays a dominant role in regulation of tumor growth in ENKTL cells, while the effect of HK2 is very small." (PMID 32203147, 2020). "Because PKM2 is a fundamental enzyme for regulation of aerobic glycolysis in tumor cells, we further determine that PTBP1 expression is positively correlated with aerobic glycolysis genes including LDHA, HK2, and ENO1." (PMID 32655719, 2020). "The result showed that the expression of HK2 was higher in ALDH1A3-positive PDAC tissues, and correlated positively with the expression of ALDH1A3 in human PDAC tumor tissues." (PMID 32612951, 2020). "HIF-1α can also promote the expression of the glycolytic enzymes, such as PKM2, HK2 and LDHA to promote glycolysis in tumors, which forms a positive feedback loop for tumor progression." (PMID 32631382, 2020). "By investigating the molecular mechanisms by which CTB exerted anti‐tumour effects by targeting mitochondria, we discovered that CTB repressed glycolysis in HCC cells, and induced HK2 dissociation from the mitochondria via VDAC1 and mPTP opening." (PMID 31994339, 2020). "Consistent with the in vitro results, immunohistological analysis revealed that AT-I downregulated the expression of HK2, p-JAK2 and p-STAT3 in tumor tissuses of the xenograft mice." (PMID 32273843, 2020). "HIF-1α accumulation contributes to glycolysis by enhancing transcription of glycolysis-related genes, including GLUT1, HK2, ALDOA, PKM2, and LDHA, which was the most important method for tumor cells to get energy and growth." (PMID 33244454, 2020). "Downregulation of HK2 or SLC2A1 dramatically impaired METTL3-induced cell proliferation and colony formation in vitro and tumor growth in vivo, which further supported HK2 and SLC2A1 (GLUT1) as critical target genes of METTL3 in CRC." (PMID 32245489, 2020). "In the tumor cells, METTL3 expression was mainly detected in the nucleus, GLUT1 and HK2 were mainly detected in the cytoplasm, but GLUT1 was also detected in the cell membrane." (PMID 32626532, 2020). "Ectopic expression of HK2 or SLC2A1 partially restored the proliferation and colony formation ability of METTL3-knockout cells and tumor growth." (PMID 32245489, 2020). "In the present case, low FDG uptake and weak expression of Glut-1, HK-2, and LDHA were observed in tumor tissue, suggesting low glycolytic activity in PLNTY." (PMID 32811569, 2020). "Moreover, we found that matrine could inhibit the expression of c-Myc and HK2, which are a transcription regulator reprogramming tumor cell metabolism and a glycolytic rate-limiting enzyme catalyzing the phosphorylation of glucose to produce glucose-6-phosphate, respectively." (PMID 31607919, 2019). "While on the contrary, mRNA levels of HK2 and LDHA genes were elevated in tumor tissues formed by Wnt3-pEX4 cells." (PMID 31632267, 2019).
tumor (continued). "The aim of this study was to investigate the relationship between IDH3a expression and glucose uptake of tumor, and to explore and elucidate the involvement of IDH3a in the AKT pathway affecting glucose uptake by detecting GLUT1 and HK2." (PMID 31355526, 2019). "The decreased expression of Hif-1α and its downstream effectors, including HK1, HK2, PKM1, and PKM2 in PD901 treated tumor cells was further confirmed by Western blotting (Sup." (PMID 30741922, 2019). "In the present study, we reported that Hexokinase 2 (HK2) is overexpressed in human CRC tissues and cell lines, knockout of HK2 inhibited cell proliferation, colony formation, and xenograft tumor growth." (PMID 31595166, 2019). "After si-HK2 treatment, the increased glucose uptake and lactate production induced by PLK3 silencing were dramatically abolished in tumor cells." (PMID 31655629, 2019). "Among four isoforms of HKs, HK1, HK2, HK3, and HK4 (also known as glucokinase), HK2 level directly and positively correlates with glycolysis level in tumor." (PMID 31607919, 2019). "Even explained the mechanisms underlying the recent observation that the combination of sorafenib and HK2 silencing increased HCC cell death, and synergistically inhibited tumor growth." (PMID 31881007, 2019). "Our results also illustrate that blocking the HectH9/HK2 pathway inhibits ROS-mediated CSC expansion and tumor development, providing a new roadmap to combat drug-resistant tumors." (PMID 31201299, 2019). "The compression-induced upregulation of ENO2, HK2, and PFKFB3 genes was confirmed in the CAF cells exposed to 0.386 kPa, the compressive stress value of a native tumor microenvironment, using real-time PCR analysis." (PMID 31428701, 2019). "To investigate the clinical correlation between B7-H3 and HK2 protein levels in CRC patient specimens, we analyzed 126 pairs of the primary tumor lesions and corresponding normal adjacent tissues in Chinese patients with CRC." (PMID 30952834, 2019). "Meanwhile, IHC staining of in vivo lung metastatic tumor tissues also showed MACC1-AS1 enhanced the expression of GLUT1, HK2, and LDH, indicating a potential role for MACC1-AS1 in glucose metabolism and redox state maintenance." (PMID 29510730, 2018). "The exemptions, i.e. NNMT, HK2, etc., were expressed in HUH7 cells as in human HCC tissues, indicating that the well-differentiated cell lines also display tumour metabolic gene expression pattern at protein level." (PMID 30176945, 2018). "For instance, pyruvate kinase type M2 and hexokinase 2, key enzymes in the glycolytic pathway of PDAC cells, contribute to the invasive potential and metastatic ability of the tumor." (PMID 30631356, 2018). "The increase in OXPHO was diminished if the cells were treated with metformin, which inhibits mitochondrial complex I. The combination of metformin and HK2 KD synergistically increased HCC cell death in vitro and tumor growth in vivo." (PMID 29386513, 2018). "HK2 localization on the OMM prevents the formation of the mitochondrial permeability transition pore, which halts apoptosis and increases tumor cell viability and resistance to chemotherapeutic agents." (PMID 29298880, 2018). "HOXA9 acts as a tumor suppressor and inhibits glycolysis in cSCC in vitro and in vivo by negatively regulating HIF-1α and its downstream glycolytic regulators, HK2, GLUT1 and PDK1." (PMID 29662084, 2018). "HK2 was most highly expressed in PDAC metastases, suggesting a link between HK2 and aggressive tumor biology." (PMID 28915575, 2017). "MiR-1 suppressed aerobic glycolysis and tumor cell proliferation via inactivation of Smad3 and targeting HIF-1α, leading to reduce HK2 and MCT4 expression, which illustrated a novel pathway to mediate aerobic glycolysis in cancer cells." (PMID 28471448, 2017). "Direct targeting of HK2 can, therefore, impede the flow of glucose into multiple downstream pathways necessary for KRAS driven tumor growth." (PMID 28915575, 2017).
tumor (continued). "In accordance with the suppression of tumor glycolysis, in all tested HCC cells, the expression of HK-2 was markedly decreased in a dose-dependent manner." (PMID 28320429, 2017). "Significantly, miR-143, a tumor suppressor in human cancers, including ESCC, and a known negative regulator of HK2, was down-regulated 1.8-fold (P = 0.0136) in the highly proliferative ZD esophagus as compared to its non-proliferative counterpart vs ZS." (PMID 29137232, 2017). "Immunohistochemistry of tumor tissues revealed that tumors administrated with IL-22 had higher p-STAT3, c-Myc, and HK2 expression than that in control group." (PMID 28445985, 2017). "This ensured that MJ dissociated the combination of HK2 and VDAC1 to block energy for tumor growth by inhibiting glycolysis." (PMID 28498814, 2017). "The mRNA levels of Glut1, Glut3, HK2, and lactate dehydrogenase A (LDHA) were dramatically higher in tumor tissues than in the adjacent normal tissues." (PMID 28445985, 2017). "UK5099 application resulted in apparently higher levels GLUT1, HK2 and LDHA protein expressions in the treated tumor cells compared to the control cells." (PMID 27911865, 2017). "N-Myc downstream regulated gene 2 (NDRG2), a tumor suppressor gene, significantly suppresses the expression of GLUT1, HK2, PKM2, and LDHA, leading to inhibition of glucose consumption and lactate production in colorectal cancer cells." (PMID 26918353, 2016). "Western blot and qRT-PCR analyses showed that the expression of GLUT1 and HK2 was decreased by FOXM1 knockdown, which was further confirmed by immunohistochemical examination of xenograft tumor sections." (PMID 27351131, 2016). "Hexokinase 2 (HK2) is a rate-determining enzyme in aerobic glycolysis, a process upregulated in tumor cells." (PMID 27260001, 2016). "Our findings here showed that the targeting of AKTs and their downstream effectors HK2 and PKM2 also contributes to miR-29b's anti-tumor function." (PMID 26512921, 2015). "We found that auraptene abolished HIF-1α protein translation and reduced transcription of HIF-1α target genes, including GLUT2, HK2 and LDHA, which are involved in regulating tumor metabolism." (PMID 26474388, 2015). "Although to a lesser extent also HK2, ALDOA and ENO2 were identified as important players for tumor progression in vivo." (PMID 25932951, 2015). "The altered glycolytic pathway in malignant tumours is activated by the upregulation of several enzymes, such as glucose tranporter-1 (GLUT-1) and hexokinase-2." (PMID 24911788, 2014). "As a tissue marker for PCa, the hK2-specific immunostaining pattern differs from that of PSA, with an increased intensity in the PCa tumour and lymph node metastases compared to that observed in benign tissue." (PMID 26116115, 2014). "Differential expression of proteins was observed between stromal and tumor cells for ENO3, GLUT1, HK2, IDH3A, LDHA and PKM2." (PMID 22412968, 2012). "RESULTS: Immunohistochemical expression of HK2 and CKA was detected in 71 (45%) and 55 (35%) tumor samples, respectively." (PMID 23071593, 2012). "Immunohistochemical analysis for HK2 and CKA expression was performed on a tissue microarray of 157 HCC tumor samples." (PMID 23071593, 2012). "Additionally, 3-bromopyruvate (3-bp), another HK2 inhibitor, has been shown to reverse L-OHP resistance in CRC, and the combination of 3-bp and L-OHP effectively suppresses tumor progression compared to L-OHP treatment alone." (PMID 40264038, 2025).
tumor (continued). "Given the central role of metabolic pathways in GBM progression, targeting alternative Warburg effect regulators like HK2, LDHA, or MCT1, which are more tumor-specific, may offer greater therapeutic benefits." (PMID 40563757, 2025). "Under 5‐FU treatment, the tumour volume of the mice in the SPARC overexpression group was significantly larger than that in the control group, and this phenomenon was inhibited by the HK2 inhibitor 2‐DG." (PMID 40415238, 2025). "Specifically, inhibiting pivotal enzymes such as hexokinase 2 (HK2) and pyruvate kinase M2 (PM2) could potentially disrupt the energy supply of cancer cells, thereby hindering tumor growth." (PMID 40933559, 2025). "Certain noncoding RNAs play regulatory roles in this process; for instance, lncRNA CASC19 can bind to small nuclear ribonucleoprotein polypeptide A (SNRPA) and subsequently upregulate the transcription of HK2 and LDHA, thereby driving tumor proliferation and metabolic reprogramming." (PMID 41415548, 2025). "In addition, the expression levels of HK2, LDHA, Glut1, and PDK1 were significantly decreased in the tumor tissues of MKN45R and HGC27R cells in the sh-SLC7A5 group." (PMID 40133832, 2025). "HK2 can be directly mediated by the m6A modifiers METTL3, YTHDF1, IGF2BP2, FTO and ALKBH5 in colorectal cancer and cervical cancer, leading to increased glycolysis, upregulated aerobic respiration in mitochondria and tumor progression." (PMID 41373022, 2025). "It has been established that HK2 binds to the outer mitochondrial membrane voltage-dependent anion channel (VDAC) in mitochondria, stabilizing the cell and enhancing ATP production, thereby supporting tumor cell growth." (PMID 39699276, 2025). "HK2 catalyzes the conversion of glucose into G6P, a key metabolite in the glycolysis, PPP and glycogen synthesis, and influences the growth and metabolism of tumor cells by regulating the transformation of fructose phosphate." (PMID 39991762, 2025). "Moreover, the glycolytic genes HK2, GAPDH and ENO1 showed elevated expression levels in INSS stage 4 tumours when compared to stage 1 tumours, highlighting the increasing energy demands associated with cancer metastasis." (PMID 41420301, 2025). "Soman effectively inhibited STAT phosphorylation in an ROS-independent manner, resulting in the decreased expression of glycolytic enzymes (HK2, PKM2, and LDHA) and activities of PK and LDH, leading to the suppression of aerobic glycolysis, cancer cell proliferation, and tumor growth." (PMID 40002413, 2025). "Furthermore, we detected significantly reduced levels of glycolytic enzymes (HK2 and LDHA) and markedly attenuated phosphorylation of PI3K and AKT in tumor samples with P3H4 silencing." (PMID 41220593, 2025). "Furthermore, by using ST, the study demonstrated significant overexpression of metabolism-related genes (e.g., HK2, PDHA1, and CS) in tumor regions, further supporting the critical role of LSM1 in regulating tumor energy metabolism." (PMID 40867511, 2025). "KD of Hk2 significantly decreased 18F-FDG uptake and tumor weight in vivo." (PMID 39883522, 2025). "Benitrobenrazide (BNBZ) and 2-DG, a direct targeted inhibitor of HK2, has been found to inhibit glycolysis in tumor cells in vivo and in vitro; Moreover, oral administration of BNBZ could significantly inhibit tumor growth." (PMID 39227970, 2024). "Upon MMP activation and cell entry, the active moiety of HK2pep displaces HK2 from MAMs, leading to a massive Ca2+ flux into mitochondria and to the ensuing tumor cell death, without off-target effects." (PMID 38995012, 2024). "HK2 is expressed in diverse cancer cell types, where it mainly localizes in MAMs, whereas it is absent in most non-tumor cells." (PMID 38995012, 2024). "In addition, HK2, ENO1, and LDHA mRNA levels were strikingly reduced in tumor tissues after KIAA1429 silencing (all P < 0.05)." (PMID 39060874, 2024).